RUVBL2 (RuvB like AAA ATPase 2)
Diseases named in the same sentence as RUVBL2 in open-access papers:
RUVBL2 is named in the same sentence as 37 diseases in open-access papers, as found by Europe PMC text mining. Sharing a sentence is not in itself a finding about the gene and the disease. The quoted sentences say what the papers report.
breast cancer (4 papers, 2013 to 2022). A primary or metastatic malignant neoplasm involving the breast. "The results showed that overexpression of RUVBL2 was associated with survival in breast cancer patients and that overexpression of RUVBL1 was associated with survival in liver cancer and cervical squamous cell carcinoma patients." (PMID 36171202, 2022). "AGR2 was also observed in the breast cancer cell lines MCF7 and H1299 to specifically bind to another protein called RuvB-like 2 (RUVBL2), which is involved in DNA repair, transcription regulation and chromatin structural control." (PMID 31247903, 2019). "Thus, RUVBL2 may contribute to tumorigenesis and cancer development; indeed, RUVBL2 overexpression has been reported in HCC, colorectal cancer, renal cell carcinoma, gastric cancer, breast cancer and salivary gland cancer." (PMID 31572066, 2019).
hepatocellular carcinoma (4 papers, 2012 to 2020). A malignant tumor that arises from hepatocytes. "Experiments showed that depleting human RUVBL1 and RUVBL2 with siRNA resulted in decreased cell proliferation and increased apoptosis in hepatocellular carcinoma cell lines." (PMID 32295120, 2020). "In case of human hepatocellular carcinoma silencing of RUVBL2 reduced cell growth and increased apoptosis whilst overexpression enhances tumorigenicity." (PMID 23443080, 2012). "Also, overexpression of RUVBL2 WB mutant repressed the function of ATF-2 and inhibited cell growth in hepatocellular carcinoma cells and leukemia cells." (PMID 32295120, 2020).
colon cancer (3 papers, 2012 to 2019). "RuvBl2 can cooperate with Ets2 to regulate the transcription of hTERT in colon cancer, and enhance tumor cell viability in HCC." (PMID 27509054, 2016). "In a separate study, on colon cancer cells, RUVBL2 was also found to regulate hTERT transcription." (PMID 22291956, 2012). "Importantly, most of WNT pathway genes induced by MYC, including DVL1, LEF1, RUVBL1, and RUVBL2, were also upregulated in tumor tissues when compared with the normal tissues from the same patients, suggesting that these genes may play a major role in colon cancer cells." (PMID 31623618, 2019).
liver cancer (3 papers, 2019 to 2022). An epithelial or non-epithelial malignant neoplasm that arises from the liver. "Taken together, RUVBL2 overexpression in liver cancer is caused by a variety of reasons, including promoter hypomethylation, chromosome gain and transcriptional regulation of TFs, etc." (PMID 31572066, 2019). "The result is consistent with a previous report, which demonstrated that knockdown of RuvBL2 by siRNAs induced apoptosis in human liver cancer cells." (PMID 34072766, 2021). "To clarify why the RUVBL2 gene is overexpressed in liver cancer, we first observed the methylation of its promoter." (PMID 31572066, 2019).
metastatic disease (3 papers, 2015 to 2024). "Finally, numerous studies have shown a critical role of RUVBL2 in controlling cell growth with overexpression responsible for oncogenesis in mixed lineage leukemia and promotion of metastatic disease." (PMID 26253138, 2015). "In particular, PSMB4, RUVBL2, and ANKAR EV protein levels were increased in patients with metastatic disease, whereas RAP2B, SERPINA12, and IGLV4-69 abundance levels were decreased in the cEVs of patients with metastasis." (PMID 39693144, 2024). "In particular, PSMB4, RUVBL2 and ANKAR EV protein levels were increased, whereas RAP2B, SERPINA12 and IGLV4-69 abundance levels were decreased in the cEVs of patients with metastatic disease." (PMID 36993200, 2024).
pancreatic cancer (3 papers, 2024 to 2025). "A comparison with KPC cells revealed that only RUVBL1, RUVBL2, TRRAP, SPT6 and WDR5 were essential in pancreatic tumours and more important for KPC cells than fibroblasts (Δlog2FC<0)." (PMID 38821858, 2024). "Analysis of The Cancer Genome Atlas (TCGA) datasets revealed that high expression of RCC1 or ACTL6A was significantly correlated with poor survival of pancreatic cancer patients (p < 0.05), whereas RUVBL2 expression was not correlated with the patient survival (p = 0.4524)." (PMID 41391757, 2025).
melanoma (2 papers, 2013 to 2019). A malignant, usually aggressive tumor composed of atypical, neoplastic melanocytes. "Interestingly, DKC1 (and partly also RUVBL2) overexpression associates consistently with unfavorable prognosis in renal, liver, head-neck, endometrial and skin (melanoma) cancers." (PMID 31750255, 2019).
viral infection (2 papers, 2014 to 2021). "In addition, we show that the viral infection-induced, RuvBL2-regulated apoptosis is counterbalanced by the survival signals of type I IFNs in infected cells." (PMID 34072766, 2021). "For example, over half of these genes have been previously associated with viral infection or replication, or have been found to physically interact with viral proteins (e.g. CLDN3; CRHR2; ILF2; ILF3; LTF; miR-122; RCHY1; and, RUVBL2)." (PMID 25079789, 2014). "Further studies demonstrated that the viral infection-induced, RuvBL2-regulated apoptosis in IAV-infected cells was overwhelmed by IFN signals, which suggests that RuvBL2 and IFNs may regulate apoptosis in IAV-infected cells through a shared pathway." (PMID 34072766, 2021).
autoimmune conditions (1 paper, 2023). "Antibody responses to F-actin, RUVBL2, and HSPD1 have been also reported in various autoimmune conditions." (PMID 37751306, 2023).
cleft lip (1 paper, 2024). Congenital defect in the upper lip where the maxillary prominence fails to merge with the merged medial nasal prominences. "One of the KS patients also carried the PROKR2 (p.Y113H) mutation, which has similar clinical manifestations to the patients in this study; the other KS patient who carried both FGFR1 (p.Gly348Glu) and RUVBL2 (p.Arg71Trp) only showed non-reproductive symptoms associated with cleft lip and palate." (PMID 38628584, 2024).
cognitive deficits (1 paper, 2026). "Elevated RUVBL2 expression drove metabolic reprogramming, while RUVBL2 knockdown inhibited this process, alleviated pro-inflammatory microglia-induced neuroinflammation and SG aggregation, and improved spontaneous neural activity and hippocampus-dependent cognitive deficits." (PMID 41931282, 2026).
influenza (1 paper, 2014). An acute viral infection of the respiratory tract, occurring in isolated cases, in epidemics, or in pandemics; it is caused by serologically different strains of viruses (influenzaviruses) designated A, B, and C, has a 3-day incubation period, and usually lasts for 3 to 10 days. "This may be a distinct and direct role for RUVBL2 in influenza replication independent of the role for the Tip60 complex in antiviral defense." (PMID 24550726, 2014).
leukemia (1 paper, 2020). A malignant (clonal) hematologic disorder, involving hematopoietic stem cells and characterized by the presence of primitive or atypical myeloid or lymphoid cells in the bone marrow and the blood. "Increased expression of both RUVBL1 and RUVBL2 in various cancer types was reported such as hepatocellular, breast, lung, leukemia, colorectal and lymphatic carcinomas." (PMID 32295120, 2020).
non-small cell lung carcinoma (1 paper, 2022). A group of at least three distinct histological types of lung cancer, including non-small cell squamous cell carcinoma, adenocarcinoma, and large cell carcinoma. "RUVBL2 is involved in DNA replication and its inhibition results in cancer cell death via cell cycle (i.e., S-phase) arrest and subsequent replication catastrophe in non-small cell lung cancer." (PMID 35406376, 2022).
prostate carcinoma (1 paper, 2013). A carcinoma that arises from epithelial cells of the prostate gland. "We show that URI interacts with RUVBL1 and RUVBL2 in the nucleus of prostate cancer cells." (PMID 23667685, 2013).
schizophrenia (1 paper, 2013). A major psychotic disorder characterized by abnormalities in the perception or expression of reality.
systemic sclerosis (1 paper, 2021). A chronic disorder, possibly autoimmune, marked by excessive production of collagen which results in hardening and thickening of body tissues. "A link between Ruvbl1 and skin biology and disease has previously been established by the observation of Ruvbl1 and Ruvbl2 autoantibodies in a subcohort of patients suffering from systemic sclerosis but not from other connective tissue diseases." (PMID 33580312, 2021).
cancer (25 papers, 2010 to 2025). A tumor composed of atypical neoplastic, often pleomorphic cells that invade other tissues. "RUVBL1 and RUVBL2 form a subcomplex of many chromatin remodeling complexes implicated in cancer progression." (PMID 39201707, 2024). "Further studies on the functions of RUVBL2 in multimolecular complexes are expected to advance our understanding of the mechanisms underlying cancers." (PMID 36171202, 2022). "RUVBL2 is associated with poor prognosis in multiple types of cancer." (PMID 35406376, 2022). "Moreover, many cancer hallmark genes were directly targeted by RUVBL2 or were immediate-early response genes bound by RUVBL2 in cancer cells, suggesting conserved RUVBL2 function in mammalian cells." (PMID 36171202, 2022). "But in addition, we also observed a strong correlation between TELO2 and RAPTOR (in nine out of 10 cancer types), mLST8 (in 10 out of 10 cancer types), mTOR, and RUVBL2 (in five out of 10 cancer types)." (PMID 40653822, 2025). "As building blocks of diverse macromolecular complexes, the AAA+ ATPases RUVBL1 and RUVBL2 are crucial for many cellular activities including cancer-related processes." (PMID 38609375, 2024). "RUVBL1 and RUVBL2 (collectively RUVBL1/2) are essential AAA+ ATPases that function as co-chaperones and have been implicated in cancer." (PMID 38609375, 2024). "The proliferation rate of cancer cells was observed to slow down significantly with a decrease in expression of RUVBL2." (PMID 37256840, 2023). "Reptin/RUVBL2 is involved in the remodeling of chromatin, DNA damage repair, and regulation of the cell cycle, all of which help to play essential roles in cancer." (PMID 35754815, 2022). "This anti-proliferative activity is surprising given the well-established oncogenic role of Ruvbl2 in a variety of cancers including renal, liver, lung, stomach, pancreas, and blood." (PMID 35178388, 2022). "We next sought to investigate the physiological relevance of the RUVBL2-Pol II axis in cancer cells." (PMID 36171202, 2022). "Conceptually, an increase in Ruvbl2lik activity that augments cardiomyocyte proliferation is consistent with the established oncogenic role of Ruvbl2 in a variety of cancers where it is significantly overexpressed." (PMID 35178388, 2022). "According to our findings, RUVBL2 plays a critical role in global transcriptional activation and Pol II clustering, suggesting a potential transcriptional amplification mechanism in cancer cells." (PMID 36171202, 2022). "Metagene analyses indicate that RUVBL2 was preferentially enriched in direct target genes compared with all genes and posttranscriptional immediate-early response genes in multiple human cancer cell lines." (PMID 36171202, 2022). "In cancer patients, RuvBL2 overexpression is considered a mark of poor prognosis, and it has been suggested as a potential anti-cancer drug target." (PMID 30213962, 2018). "RUVBL1/2 is upregulated in a variety of cancers, including colon and liver and the ATPase activity of RUVBL2 was shown to be required for sustained growth and viability of these tumor cells." (PMID 26201077, 2015). "RUVBL1 is a highly conserved AAA(+) ATPase whose expression as well as expression of its homolog RUVBL2 was high in different cancers." (PMID 23443080, 2012). "Besides regulating the cell response to stress conditions, RuvBL1 and RuvBL2 have known implications in cancer." (PMID 30213962, 2018). "In cancer patients, RuvBL2 overexpression is considered a marker of poor prognosis." (PMID 30213962, 2018). "In addition, RuvBl1 (Pontin) and RuvBl2 (Reptin) are overexpressed in a variety of human cancers." (PMID 20426839, 2010). "RUVBL1 and RUVBL2, referred to as RUVBL1/2, are crucial AAA+ ATPases that act as co-chaperones and are connected to cancer." (PMID 38609375, 2024). "Most of these genes were cell cycle-related genes, including CHEK1, CDK1, RUVBL2, PSMD14, SUPT5H, RBX1, and AURKA, across 28 cancer types." (PMID 38972884, 2024).
cancer (continued). "Overexpression of RUVBL1, RUVBL2, ILF2, ILF3, and HNRNPM are observed in various cancers with their progression (RUVBL1 and RUVBL222,46, ILF2 and ILF347–49, HNRNPM50,51)." (PMID 38225262, 2024). "Though antibody responses to F-actin, RUVBL2, and HSPD1 have been reported in other cancers, they are here identified to induce B cell response in PDAC." (PMID 37751306, 2023). "They found that Liddean affected the oligomeric state of RUVBL2 and led to a shift of RUVBL1/2 complex localization from the cytoplasm to the nucleus in cancer cells." (PMID 32295120, 2020). "Significantly, RUVBL2 was found to be recruited to the promoter of KAI-1 in a complex with β-catenin resulting in the repression of KAI-1 expression, a metastasis suppressor protein, thus contributing to the enhanced invasion ability of cancer cells." (PMID 32295120, 2020). "Recently, RuvB-like 2 (RUVBL2) was found to interact with catenin beta 1 (CTNNB1), telomerase reverse transcriptase (TERT), MYC proto-oncogene (MYC), nuclear factor-kappa B1 (NFKB1), etc. to regulate the cancer-related signaling pathways in HCC." (PMID 31572066, 2019).
tumor (13 papers, 2013 to 2025). "Our results showed that high RUVBL2 mRNA expression was associated with poor differentiation of HCC tumor, which is in agreement with a previous report." (PMID 31572066, 2019). "The key genes, CDK2, MCM7, and RUVBL2, have all been observed to have an increased level of expression for adolescent hosts irradiated with protons, which likely contribute to the picture of an overall environment predisposed to both oncogenesis and tumor promotion." (PMID 26253138, 2015). "Moreover, when the samples of tumor tissues were expanded to 371 cases, RUVBL2 mRNA remained at an approximately 1.3-fold increase in HCC (P < 0.0001)." (PMID 31572066, 2019). "RUVBL2 mRNA was significantly upregulated in tumor tissues (P < 0.0001)." (PMID 31572066, 2019). "Combining these observations, it is conceivable that, when a tumor reaches hypoxic state, overexpression of RuvBL2, and its consequent methylation en masse, may contribute to a large-scale downregulation of the target genes." (PMID 30213962, 2018). "Selective knockdown of RuvBL2 rescued cells from PCI-24781-induced cell death, implying that RuvBL2 might play an important role in anti-tumor activity of PCI-24781 in SK-N-DZ cells." (PMID 23977108, 2013). "However, some were also essential for tumours in their natural environment and, among these, the ATPases RUVBL1 and RUVBL2 ranked first." (PMID 38821858, 2024). "Furthermore, the expression levels of RAC1, CDK2, RUVBL2, and MET were upregulated in the tumor group compared to the control group and showed a noticeably positive correlation with the expression level of RHOA." (PMID 35406376, 2022). "According to the RNA sequencing data from TCGA, we first observed RUVBL2 expression between primary tumor and paired adjacent noncancerous tissues (n = 50)." (PMID 31572066, 2019). "Importantly, this study also demonstrated that Reptin (RUVBL2) plays a similar role in stabilising ATM kinase, highlighting its key function in facilitating the repair of double-strand breaks (DSBs) in HCC cells and promoting genomic stability in tumour progression." (PMID 40256842, 2025).
infection (5 papers, 2014 to 2024). The state of being infected such as from the introduction of a foreign agent such as serum, vaccine, antigenic substance or organism. "Knockdown of RuvBL2 by siRNAs induced apoptosis and overexpression of RuvBL2 resulted in increased resistance to infection-induced apoptosis in Vero cells." (PMID 34072766, 2021). "Infection of interferon (IFN)-deficient Vero cells with wild-type or delNS1 PR8 virus reduced RuvBL2 protein levels and induced apoptosis; delNS1 virus caused more reductions in RuvBL2 protein levels and induced more apoptosis than did wild-type virus." (PMID 34072766, 2021). "In contrast to Vero cells, infection of IFN-competent A549 cells with PR8 virus caused reductions in RuvBL2 protein levels but did not induce apoptosis." (PMID 34072766, 2021). "Therefore, we wanted to determine whether infection with HAdVs affects the ability of RuvBL1 to interact with RNA polymerase II or RuvBL2." (PMID 38940561, 2024). "Because IAVs have evolved several strategies to suppress IFN production in infected cells, it is possible that the infection-induced, RuvBL2-regulated apoptosis may play a significant role in IAV-induced apoptosis even in IFN-competent cells under certain circumstances." (PMID 34072766, 2021). "Three of these IAV host factors also regulate infection by SARS-CoV-2, acting as pro-viral (COPB1, AHNAK) or antiviral (RUVBL2) factors of SARS-CoV-2 infection." (PMID 37758692, 2023). "Specifically, suppression of IFI6 and OAS1 was impaired by HAdV-B7 when RuvBL2 was knocked down, but not of IFIT1 nor IFIT2, while only OAS1 expression in HAdV-B14 infection was affected by RuvBL2 knockdown." (PMID 38940561, 2024). "Infection of human lung A549 cells with PR8 virus resulted in a reduction of the protein levels of RuvBL2 but not RuvBL1." (PMID 34072766, 2021). "PR8 virus induces apoptosis in infected cells by suppressing the protein levels of RuvBL2 in the absence of IFN influence, and the NS1 protein inhibits infection-induced apoptosis by maintaining RuvBL2 protein abundance." (PMID 34072766, 2021). "Loss of RUVBL1, RUVBL2, or TIP60 mosquito orthologs did not affect cell number but led to a significant increase in WNV-KUN infection (p<0.05)." (PMID 24550726, 2014). "In contrast to RuVBL2, the infection had no apparent effect on RuvBL1 protein levels." (PMID 34072766, 2021). "RUVBL2, ADNP, SF3A2, CDK2, PRKDC, and NONO were particularly interesting as the increase in acetylation following SIRT2 inhibition temporally aligned with the time point of maximal interaction with SIRT2 during infection." (PMID 37916830, 2023).
RUVBL2 also shares sentences with these, for which no sentence is quoted: neuroblastoma (2 papers); autoimmune disease (1); cervical squamous cell carcinoma (1); ciliopathy (1); cognitive decline (1); colorectal cancer (1); colorectal tumors (1); connective tissue diseases (1); Fanconi anaemia (1); gastric cancer (1); Hepatic fibrosis (1); Immunodeficiency (1); Kidney Cyst (1); renal cell carcinoma (1); salivary gland cancer (1); Seckel syndrome (1); varicocele (1).